RRM2B (ribonucleotide reductase regulatory TP53 inducible subunit M2B)
Diseases named in the same sentence as RRM2B in open-access papers (continued):
Sharing a sentence is not in itself a finding about the gene and the disease.
cancer (continued). "Whereas RRM2B overexpression led to a reduction in the cell number, the expression of RRM2BshRNA led to an increase in MTS readings, compared with that of the respective controls; these results suggest that RRM2B inhibits the growth of cancer cells (Figures 4bi and 4bii)." (PMID 24947616, 2014). "Furthermore, RRM2B can suppress metastasis and inhibit proliferation in certain cancer cells, and RRM2B is the only RR subunit that has been identified as being capable of counteracting the actions of reactive oxygen species (ROS), which makes it unique." (PMID 24947616, 2014). "At present, there are no known RRM2B germline alterations associated with cancer risk." (PMID 33868369, 2021). "Importantly, for the first time, we revealed the correlations among RRM1, RRM2, and RRM2B expression during cancer development as well as their individual roles and collaborative relationships during cancer progression together with their prognosis with clinical tumor sample validation." (PMID 31637211, 2019). "However, the RRM2B signaling pathway is complex because the expression of RRM2B has been reported to correlate with either enhanced survival or an increase in the progressive phenotype in tissues of patients with various cancers." (PMID 24947616, 2014). "Cancer cells and primary cells express RRM2, which theoretically should be able to maintain dNTP pools when RRM2B is silenced." (PMID 26733354, 2016). "The proportion of RRM2B-positive cells increased as the FOXO3 levels increased (P < 0.0001), and high expression of nuclear FOXO3 coincided with RRM2B expression in cancer patients." (PMID 24947616, 2014). "In most cancers, the mRNA expression of RRM1, RRM2, and RRM2B was generally increased." (PMID 36713030, 2023). "Hereby we demonstrate that ccRCC depends on the expression of AGPAT6, GALT, GCLC, GSS, and RRM2B, which, although essential for cancer cells, are potentially nonessential in normal cells." (PMID 26040780, 2015). "To test this, we introduced a FOXO3-targeting siRNA into cancer cells and examined whether downregulating FOXO3 affects RRM2B levels." (PMID 24947616, 2014). "RRM2B expression was reversely correlated with cell cycle-promoting molecules in LUAD but not in LUSC, suggesting that RRM2B may directly or indirectly suppress cell cycle progression, hence cancer cell proliferation, in LUAD." (PMID 31637211, 2019). "Moreover, Overexpression of RRM2B and/or FOXO3 inhibited the proliferation of cancer cells." (PMID 24947616, 2014). "All RRM2B aberrations except one were found in non-luminal A cancers." (PMID 24215511, 2013). "Our study also suggests that RRM2B-specific inhibitors, if can be developed, will be promising anti-cancer agents to be combined with standard treatment for its critical role in drug resistance and relapse of cancer cells but the non-essential role in normal cells." (PMID 36882565, 2023).
tumor (29 papers, 2005 to 2026). "Here, we tested whether RRM2B amplifications are associated with specific tumor mutational signatures." (PMID 33868369, 2021). "RRM2B is a ribonucleotide reductase that contributes to DNA repair by supplying deoxynucleotide triphosphate pools in response to DNA damage, and has been associated to treatment sensitivity and tumour invasiveness." (PMID 22905093, 2012). "By integrating multiomics data, we identified TK1, NME4, and RRM2B as key biomarkers that influence tumor progression, immune modulation, and treatment response." (PMID 41584726, 2026). "To determine if the RNR M2 subunit switching we observed in vitro occurred in vivo, we collected HB214 tumors two days and 34 days post irinotecan treatment and performed RRM2 and RRM2B RNAscope staining on tumor sections." (PMID 36882565, 2023). "To explore the clinical implications of RR subunits, we compared the differences of RRM1, RRM2, and RRM2B among clinicopathologic features, including age, race, gender, T stage, grade, stage, tumor status, and alpha-fetoprotein (AFP) level." (PMID 36713030, 2023). "A reversed RRM2B-to-RRM2 switching was evident in the relapsed tumor 34 days post treatment with the regaining of RRM2 punctate signals and its association with Ki67 positivity when RRM2B dropped." (PMID 36882565, 2023). "Overall, this study provides an in-depth analysis of RRM2B alterations in multiple tumor types, majorly reflected as RRM2B amplifications in conjunction with MYC, and other genes on chromosome 8." (PMID 33868369, 2021). "We found that RRM2B is highly amplified in multiple tumor types, particularly in MYC-amplified tumors, and is associated with increased RRM2B mRNA expression." (PMID 33868369, 2021). "To validate this relationship between DNA repair genes and potential oncogenic or tumor suppressive roles, we utilized the TCGA database to analyze NEIL2 and RRM2B, the repair genes with the highest frequency of CNV loss and gain, respectively." (PMID 27004405, 2016). "Both tumor samples showed a markedly higher level of RRM2B than RRM2." (PMID 36882565, 2023). "Interestingly, limited overlap was found between the two tumor types for their RRM2 or RRM2B hub genes." (PMID 36882565, 2023). "In addition, we found that LUSC had higher RRM1 and RRM2 expression than LUAD, while RRM2B expressed lower in tumor tissues of LUSC than in those of LUAD." (PMID 31637211, 2019). "In this study, we discovered tumor suppressor FOXO3 as the novel regulator of RRM2B." (PMID 24947616, 2014). "The data form GENT indicated an upregulation in the expression of METTL3, RRM2B, OPA1 and IGF2BP2 in CRC tumor tissues compared with normal tissues." (PMID 38549713, 2024). "In the remaining viable tumor cells within these two tumors, we found much lower levels of RRM2 but higher levels of RRM2B compared to PT1 (vii & xi vs. iii, viii & xi vs. iv)." (PMID 36882565, 2023). "The results showed that RRM1 and RRM2 protein mainly localized in the cytosol while RRM2B protein was found in both the cytosol and nucleoplasm of LUSC and LUAD tumor cells." (PMID 31637211, 2019). "At the end of the experiment, the tumor volumes and weights in the sh-METTL3 group were significantly lower than those measured in the sh-control group, and these effects were reversed by overexpression of RRM2B or OPA1." (PMID 38549713, 2024). "Interestingly, while THCA genetic profiles revealed that only 2% of evaluated patient tumor samples had CNAs in RRM2B, bulk mRNA expression of RRM2B was highest in THCA tumor samples." (PMID 36831501, 2023). "Our IHC examination of NSCLC tumor tissue and immunofluorescent images of three cell lines in the HPA have demonstrated that both RRM1 and RRM2 are mainly expressed in the cytoplasm, whereas RRM2B is expressed both in the cytoplasm and the nucleus." (PMID 31637211, 2019).
tumor (continued). "Because HB is very rare, and nearly all children with HB receive neoadjuvant chemotherapy prior to tumor resection, we were unable to obtain matched pre- and post-treatment patient tumor samples to directly determine treatment-induced changes in RRM2 and RRM2B expression." (PMID 36882565, 2023). "Similarly, RRM2B (nucleotide biosynthesis), PRKAA1 (AMPK signaling), and RICTOR (mTOR signaling) had widespread copy number gains exclusively in glycolytic cancers, apart from RRM2B, which had copy number gains in ~30% of evaluated PRAD patient tumor genes." (PMID 36831501, 2023). "However, no RRM2B-specific inhibitors have been developed likely due to the low expression of this RNR M2 subunit in growing tumor cells." (PMID 36882565, 2023). "Thus, except for RRM2B, the expression levels of the group of proteins involved in mitochondrial and nuclear DNA replication decreased following long-term treatment of the GBM tumor with si-hVDAC1." (PMID 31661894, 2019). "RRM2B CNAs were not as abundant in KIRC, but were the highest alteration in PRAD tumor samples, with 33% of evaluated PRAD samples having a gain or amplification in RRM2B copy number." (PMID 36831501, 2023).
mitochondrial disease (13 papers, 2011 to 2025). "In summary, previous studies into deoxynucleoside supplementation as a therapy for mitochondrial disease due to pathogenic RRM2B variants have been performed on in vitro models that focus mainly on manipulation of mtDNA copy number." (PMID 40211788, 2025). "Surprisingly, this included 3 genes with a literature reported function in mitochondrial metabolism, in which pathogenic variants are a well-known cause of mitochondrial disease (RRM2B, c19orf12, TAZ)." (PMID 30369941, 2018). "We, therefore, conducted a systematic clinical and molecular study of adult patients with RRM2B mutation(s) to define the phenotypic spectrum of adult RRM2B-related mitochondrial disease and establish any genotype–phenotype correlations." (PMID 23107649, 2012). "RRM2B mutations are emerging as one of the leading causes of both paediatric and adult-onset mitochondrial disease associated with disruption of mitochondrial DNA maintenance." (PMID 23107649, 2012). "Twenty-one patients with confirmed RRM2B mutations underwent a diagnostic muscle biopsy for the investigation of suspected mitochondrial disease." (PMID 23107649, 2012). "The most severe form of RRM2B-related mitochondrial disease is associated with mitochondrial DNA depletion." (PMID 23107649, 2012). "Together this data further adds to the growing evidence that deoxynucleoside supplementation is a valid therapeutic approach for treating patients with pathogenic RRM2B variants and possible also for other forms of mitochondrial diseases caused by mtDNA depletion." (PMID 40211788, 2025). "Notably, mutations in SPG7 (≈4/100,000) and PEO1 (≈3/100,000), followed by OPA1 (≈1/100,000) and RRM2B (≈0.9/100,000) have emerged as major causes of adult mitochondrial disease." (PMID 25652200, 2015). "Furthermore, RRM2B-related mitochondrial diseases are frequently inherited and associated with neurological symptoms." (PMID 26339226, 2015). "The RRM2B-related mitochondrial disease also leads to distinct clinical and molecular characteristics including depression." (PMID 37398042, 2023). "A growing number of mitochondrial diseases with mtDNA instability have been linked to mitochondrial deoxynucleotide pool imbalance, including deficiencies of TK2, dGK, RRM2B or TYMP." (PMID 29602790, 2018). "Because all other RRM2B mutations reported to date in this disease group are either missense or exon 9 truncating, our data further expand the molecular heterogeneity of RRM2B-related adult mitochondrial disease." (PMID 23107649, 2012). "Also, patients with mitochondrial diseases affecting muscle argue against this (TK2, SUCLA2, SUCLG1, RRM2B, DGUOK, and TYMP)." (PMID 30538797, 2018).
myopathy (4 papers, 2013 to 2024). A disease of the muscle in which the muscle fibers do not function properly. "A less severe PEO, ptosis, and myopathy phenotype, manifesting before early adulthood, is associated with dominant RRM2B variants causing mtDNA multiple deletions, with less frequent or severe multisystemic features." (PMID 38804971, 2024). "All the patients with autosomal recessive RRM2B mutations described until now have had myopathy and most of them have had renal involvement." (PMID 24382854, 2013). "Curiously, recessive RRM2B variants often cause even more severe, rapidly progressive and multisystemic mtDNA depletion syndromes with severe myopathy, gastrointestinal, nervous system (MNGIE-type), and sometimes renal disease, which are often fatal within infancy." (PMID 38804971, 2024). "Loss of Rrm2b in the myofibers may cause more severe myopathy than loss in the MuSCs." (PMID 35906243, 2022). "The demonstration of severe mtDNA depletion prompted screening of genes associated with mtDNA depletion myopathy (TK2 and RRM2B) in subjects 1 and 2 prior to WES." (PMID 27693233, 2016). "Patients with myopathy were found to have genetic defects in RRM2B and decreased RRM2B expression." (PMID 35906243, 2022).
peripheral neuropathy (3 papers, 2013 to 2022). A disorder affecting the peripheral nervous system. "Peripheral neuropathy has been reported in only a small number of patients with PEO and C10orf2 or RRM2B mutations." (PMID 25281868, 2014). "This is an important finding because until now peripheral neuropathy has not been described in patients with RRM2B mutation, but only in patients with POLG mutation." (PMID 24382854, 2013).
infection (2 papers, 2012 to 2025). The state of being infected such as from the introduction of a foreign agent such as serum, vaccine, antigenic substance or organism. "The presence of background infection in HU-treated cells with high titer virus challenge, despite using higher inhibitor concentrations, could be attributed to the more pronounced inhibition of RRM2, but not RRM2B, by HU." (PMID 40586616, 2025).
RRM2B also shares sentences with these, for which no sentence is quoted: lymph node metastasis (3 papers); melanoma (3); acute myeloid leukemia (2); esophageal cancer (2); gastric cancer (2); lymphoma (2); neurological disease (2); oral cancer (2); prostate carcinoma (2); adenocarcinoma (1); AIDS (1); autosomal dominant deafness (1); autosomal dominant disease (1); autosomal dominant progressive external ophthalmoplegia (1); autosomal recessive disease (1); autosomal recessive progressive external ophthalmoplegia (1); bladder cancer (1); chronic progressive external ophthalmoplegia (1); Cohen syndrome (1); focal segmental glomerulosclerosis (1); Gitelman syndrome (1); head and neck squamous cell carcinoma (1); HIV-1 infection (1); Insulin resistance (1); kidney disease (1); leukemia (1); lipid storage myopathy (1); lung adenocarcinoma (1); lung sarcomatoid carcinoma (1); metabolic disorders (1).
A further 23 diseases each share a sentence with RRM2B in 1 paper.